IL24 (interleukin 24)
Diseases named in the same sentence as IL24 in open-access papers (continued):
Sharing a sentence is not in itself a finding about the gene and the disease.
melanoma (continued). "Previous studiessuggest that IL-24 selectively kills melanoma cells via an IL-20 receptor-dependentpathway that is independent of STAT3.In melanoma tumor cells, IL-24 induces IFN-α, which leads to growth inhibitionand apoptosis, possibly involving FAS-FASL and TRAIL interactions." (PMID 22569271, 2012). "Furthermore, induction of terminal differentiation in melanoma cells with fibroblast interferon and mezerein lead to an increase in IL-24 mRNA expression primarily through an increased stability of IL-24 mRNA." (PMID 20072629, 2010). "Finally and importantly, five different routes of IL-24 administration, including intracellular over-expression, were evaluated for their potential to kill a selection of melanoma cell lines." (PMID 18074024, 2007). "The first interest in IL-24 as a possible therapeutic agent for cancer came from observations that IL-24 transcripts or protein were gradually lost during advanced invasive progression of melanoma." (PMID 18074024, 2007). "IL-24 mRNA was detectable to various levels in 6 out of 10 melanoma cell lines." (PMID 18074024, 2007). "This throws into doubt whether IL-24 can exert so-called bystander effects on melanoma cells as these are believed to depend on the presence of receptors." (PMID 18074024, 2007). "Interestingly, while IL-24 expression did not correlate with overall survival in melanoma patients, it was associated with improved survival outcomes in patients treated with anti-PD-1 therapy." (PMID 40866941, 2025). "Collectively, these findings highlight vinburnine as a promising candidate for melanoma treatment and suggest that targeting the IL-24/IL-20R2 axis may offer broader therapeutic benefits across multiple cancer types, particularly in combination with immune checkpoint inhibitors." (PMID 40866941, 2025). "Hence, melanoma cells require some basal level of IL24 gene expression to support proliferation." (PMID 38414326, 2024). "However, IL-24 molecular mechanisms and signaling pathways underlying melanoma suppression were not described and even less in combination with EGFR targeted therapy." (PMID 33918490, 2021). "We found that F5/35‐ZD55‐IL‐24 could efficiently deliver IL‐24 to melanoma cells." (PMID 30406970, 2018). "Interestingly, the IL-24 level is again upregulated upon forced differentiation of melanoma cells." (PMID 27387763, 2016). "However, in melanoma tissues IL-24 mRNA but not the protein was detectable suggesting loss of IL-24 protein expression occurred during cellular transformation." (PMID 24377906, 2013). "Some previous papers also show iNOS was found to be increased in advanced stages of melanoma and expression of MDA-7/IL-24 negatively regulated iNOS expression in malignant melanoma cell lines, suggesting that iNOS might contribute to enhance tumor progression." (PMID 22629368, 2012). "Furthermore, intra-tumoral administration of ad.mda-7 in a phase I clinical trial showed evidence of clinical tumor suppressor effects and in support of the tumor suppressor effect of IL-24, there appears to be an inverse correlation between IL-24 expression levels and melanoma progression." (PMID 20072629, 2010). "Further investigation revealed that melanoma cells increased the expression of GADD family members—GADD153, GADD34, and GADD45α—in response to IL‐24." (PMID 40338095, 2025). "Three of the five melanoma lines tested were sensitive to increasing concentrations of WX8, and the two most sensitive lines also had the highest basal levels of IL24." (PMID 38414326, 2024). "PIKFYVE inhibitor WX8 in sensitive melanoma cells and tumors induces the PERK-dependent ER-stress response with concomitant upregulation IL24 expression." (PMID 38994949, 2024). "At least 30% of the melanoma cell lines tested were PIKFYVE‐sensitive, and the cell lines that were most sensitive to WX8 also upregulated IL24 expression the most." (PMID 38414326, 2024).
melanoma (continued). "In contrast with melanoma, osteosarcoma U2OS cells had the highest basal level of IL24 RNA and adenocarcinoma HCT116 had the lowest, but their sensitivity to WX8 was the same." (PMID 38414326, 2024). "Inhibition of PIKFYVE activity induced IL24 expression with concomitant amplification of the PERK‐dependent ER‐stress response, which resulted in the termination of autophagy‐dependent melanoma cells in vivo as well as in vitro." (PMID 38414326, 2024). "RNA sequence profiling suggested that PIKFYVE inhibitors upregulated an endoplasmic reticulum (ER) stress response involving interleukin‐24 (IL24; also known as MDA7) selectively in melanoma cells." (PMID 38414326, 2024). "In human melanoma (A375) cells, the HDAC inhibitors, sodium butyrate and Trichostatin A (TSA), upregulate MDA-7/IL-24 expression and downregulation is observed upon overexpression of the HDAC4 enzyme." (PMID 35008495, 2021). "MDA-7/IL-24-expressing T cells (T-MDA-7) were superior to unmodified T cells in suppressing primary mouse prostate cancer and melanoma as well as inhibiting cancer metastases." (PMID 35008495, 2021). "To assess the anti-cancer effect of IL-24-iMSCs in the tumor-bearing mouse model, we performed subcutaneous injection of 5 × 105 B16-F10 cells in the C57BL/6 to generate melanoma-bearing mice." (PMID 32015693, 2020). "According to our study, we now know that the overall anti-melanoma efficacy of ZD55-IL-24 in patients should be contributed by the direct killing pathway, antitumor immunity pathway, IL-24-mediated other antitumor pathway, and anti-angiogenesis pathway." (PMID 33257647, 2020). "F5/35‐ZD55‐IL‐24 induced higher expression of IL‐24 than did ZD55‐IL‐24 in melanoma cells and showed high infectivity of melanoma cells in a vector dose‐dependent manner." (PMID 30406970, 2018). "In keeping with a previous study on melanoma cells, insertion of the 3′ UTR of IL-24 mRNA induced degradation of the β-globin reporter mRNA in our assay." (PMID 20072629, 2010). "Initially, a panel of 12 different melanoma cell lines, the immortalised keratinocyte line HaCaT and primary human melanocytes (NHEM), were evaluated for classic Jak-STAT activation following IL-24 stimulation." (PMID 18074024, 2007). "To determine whether Vin upregulates IL-24 expression through the P38/MAPK/ATF3 signaling pathway, we treated melanoma cells with the P38 inhibitor SB203580 in combination with Vin." (PMID 40866941, 2025). "IL-24 protein expression was evident in normal melanocytes, skin smooth muscle cells, and early-stage melanomas, but was notably absent in more advanced tumors." (PMID 40806452, 2025). "Adenovirus‐overexpressing IL‐24 prompted apoptosis and induced G2/M cell cycle arrest in melanoma cells, while showing no such impact on normal human melanocytes." (PMID 40338095, 2025). "Interleukin-24 (IL-24), a member of the IL-10 superfamily first identified as a negative regulator of human melanoma, has demonstrated bystander antitumor effects without cytotoxic activity toward normal cells." (PMID 41288708, 2025). "Ablation of the IL24 gene in melanoma cells prevented cell death, and ectopic expression of IL24 induced cell death in melanoma cells but not in human fibroblasts." (PMID 38994949, 2024). "Since expression of IL24 gene is controlled by transcription factors CEBPb, JUN, and FOS, induction of PERK stem of ER stress transcription factor DDIT3 upregulated IL24 expression which resulted in melanoma cell death." (PMID 38994949, 2024). "Moreover, induction of cell death by a PIKFYVE inhibitor together with ectopic expression of IL24 protein was cumulative, thereby confirming the therapeutic potential of PIKFYVE inhibitors in the treatment of melanoma." (PMID 38414326, 2024).
melanoma (continued). "And other scholars conducted a comparative analysis between the impacts of IL-24 -engineered iMSCs (IL-24-iMSCs) and conventional iMSCs in melanoma, establishing that IL24-iMSCs exhibit superior efficacy in restraining melanoma growth compared to the control iMSCs." (PMID 39135947, 2024). "Thus, PIKFYVE inhibitors, either alone or in combination with other targeted drugs (including ectopic IL24 protein) exhibit significant therapeutic potential against PIKFYVE‐sensitive cancers, particularly melanoma that express high levels of endogenous IL24." (PMID 38414326, 2024). "Ectopic expression of IL24‐induced cell death in melanoma cells, but not in foreskin fibroblasts, whereas ablation of the IL24 gene in melanoma cells prevented death." (PMID 38414326, 2024). "Based on profound and selective antitumor activity in vitro and in animal models, a replication incompetent type 5 Ads expressing MDA-7/IL-24 (Ad.5-mda-7; INGN-241) was tested in a Phase I clinical trial in patients with advanced cancers, including melanomas and carcinomas." (PMID 35008495, 2021). "MDA-7/IL-24 protein induced phosphorylation and nuclear translocation of STAT3 in melanoma cells via both type 1 and type 2 IL-20R and induced dose-dependent cell death in melanoma tumor cells." (PMID 35008495, 2021). "mda-7/IL-24 was first identified and cloned using a differentiation induction subtraction hybridization (DISH) screening approach with metastatic human melanoma cells induced to terminally differentiate by treatment with recombinant human interferon and the protein kinase C activator mezerein." (PMID 31489119, 2019). "In a phase I/II clinical trial a replication incompetent adenovirus expressing mda-7/IL-24, Ad.mda-7 (INGN 241) (2 × 1010 to 2 × 1012 vp) was administered intratumorally in a cohort of 28 patients with melanomas and advanced carcinomas and injections were repeated in a dose-escalating manner." (PMID 31489119, 2019). "Similarly, MITF and BPTF co-repress SASP genes like SERPINE1, IL24, PDGFB, and CYR61 as well as ZEB1 that has a crucial role in melanoma progression." (PMID 26440048, 2015). "Overall and relative to control treatments, no cancer-specific apoptosis-inducing properties of IL-24, even when over-expressed from within melanoma cells, were recorded." (PMID 18074024, 2007). "Although these transfection efficiencies were acceptable for melanoma cells, they are, however, not optimal and certainly far lower than those achieved with adenoviral expression of IL-24." (PMID 18074024, 2007). "Here we show that melanoma cells did not respond to IL-24, neither when up to 800 ng/ml of cytokine was administered, nor over different periods of time." (PMID 18074024, 2007). "In stark contrast to its “normal” and physiological behaviour, IL-24 has been reported to selectively and efficiently kill a vast variety of cancer cells, especially melanoma cells, independent of receptor expression and Jak-STAT signalling." (PMID 18074024, 2007). "No increased apoptosis was observed in any of the tested scenarios when compared to appropriate control treatments and therefore we conclude that the cytokine IL-24 itself is not sufficient to selectively drive melanoma cells into apoptosis." (PMID 18074024, 2007). "Lastly, in melanoma models, administration of IL‐24 was shown to reduce the expression of inducible nitric oxide synthase (iNOS), suggesting a negative correlation between IL‐24 and iNOS." (PMID 40338095, 2025). "Thus, PIKFYVE activity prevented over‐expression of IL24 in melanoma cells, whereas PIP4K2C did not." (PMID 38414326, 2024). "A more advanced version, ZD55-IL-24, which contains the interleukin (IL-24) and retains a functional E3 region, has shown the ability to effectively combat melanoma by converting tumor cells from the nonself state as well as through the classic direct killing pathway." (PMID 38528632, 2024).
melanoma (continued). "Thus, we conclude that the cytokine IL-24 itself has no cancer-specific apoptosis-inducing properties in melanoma cells." (PMID 18074024, 2007). "Even up to 20 μg of transfected IL-24 DNA did not result in a surplus of apoptotic cells compared to control experiments, once more demonstrating that even intracellular over-expression does not lead to a specific killing of melanoma cells in response to full length or ER-targeted IL-24." (PMID 18074024, 2007). "Having established that commercially available recombinant cytokines expressed in mouse myeloma NSO cells (IL-24) or bacteria (IL-19, -20) have no growth-modulating effect on melanoma cells, we continued to examine different sources of recombinant IL-24 for their impact on melanoma cells." (PMID 18074024, 2007). "Since no Jak/STAT signalling was detected in any of the melanoma cell lines following IL-24 (or IL-19 and IL-20) treatment, the expression of the 3 possible receptor chains was analysed by standard RT-PCR, quantitative PCR (qPCR), Western Blot and FACS analyses." (PMID 18074024, 2007). "Hence, the “bystander” effect that secreted IL-24 has been reported to have on receptor-positive cancer and melanoma cells is difficult to reconcile with the lack of receptors found here." (PMID 18074024, 2007). "Additionally, in some epithelial cancers such as non‐small cell lung cancer (NSCLC) and melanoma, as well as hematopoietic tumors like diffuse B‐cell lymphoma and Burkitt lymphoma, the absence of IL‐24 protein expression correlates with disease stage and is indicative of a poorer prognosis." (PMID 40338095, 2025). "Similarly, our further data revealed that the anti-melanoma efficacy of ZD55-IL-24 had no significant enhancement compared with ZD55 and ZD55-EGFP, further supporting the conclusion that the exogenous IL-24 gene played no role in B16-bearing immunocompetent mouse model." (PMID 33257647, 2020). "Using crude or affinity purified Hek-IL-24, again no increase in apoptosis or reduced proliferation was observed relative to untreated cells or cells treated with accordingly produced IL-20 and this was not surprising as the tested melanoma cell lines did not express functional IL-24 receptors." (PMID 18074024, 2007). "Taken together, melanoma cell lines evaluated in this study did not express sufficient amounts of specific receptor pairs, which could mediate effects brought about by the cytokine IL-24." (PMID 18074024, 2007). "Additionally, IL-24 produced from transfected Hek cell supernatants (lanes 6), which will be discussed in more detail below, also induced phosphorylation of STAT3 in HaCaT cells but not in any of the melanoma cell lines." (PMID 18074024, 2007).
breast cancer (47 papers, 2007 to 2026). A primary or metastatic malignant neoplasm involving the breast. "To assess the effect of IL-24 expression on human breast cancer, we interrogated The Cancer Genome Atlas (TCGA) database for the association between IL24 expression and survival in the breast cancer cohort." (PMID 39782693, 2025). "The CXCL12/CXCR4 signaling axis is regulated by the tumor suppressor gene Il-24 and is strongly associated with breast cancer." (PMID 40076586, 2025). "This is the first demonstration that TXNIP positively affects IL-24 expression in breast cancer cells, although the mechanism underlying this positive correlation is unclear." (PMID 40175348, 2025). "Both IL24 and IL32 have tumor suppressing properties where reduction in IL24 levels has been observed in breast cancers and was associated with poor prognosis and severe clinical outcomes." (PMID 29922517, 2018). "We have previously shown that growth suppression by mda-7/IL-24 is associated with transcriptional up-regulation of p27Kip1 via Stat3 activation in breast cancer cells." (PMID 26460950, 2015). "IL-24 expression is associated with improved prognosis in human breast cancer." (PMID 39782693, 2025). "The levels of Interleukin 24 (IL-24), a cytokine that inhibits tumor progression, and its receptor, the IL-24 receptor (IL-24R), are found to be reduced in breast cancer samples and are associated with increased levels of lymph-specific markers, such as podoplanin, PROX1, and LYVE-1." (PMID 35885529, 2022). "To further evaluate whether IL-24 induction by calcipotriol was linked to CD4+ T cell infiltration in mammary tumors, we assessed the colocalization of IL-24–expressing cells with CD4+ T cells in PyMt tumors of WT mice treated with EtOH, calcipotriol, or calcipotriol plus anti-CD4 Ab." (PMID 39782693, 2025). "To determine whether the IL-24/IL-20R axis contributed to calcipotriol-mediated mammary tumor suppression, we first examined the association between IL-24 induction by calcipotriol in the TME and the tumor cell expression of IL-22Rα and apoptosis marker, cleaved caspase-3." (PMID 39782693, 2025). "Functional studies demonstrate that IL-24 signaling through its receptor, IL-20R, is required to induce mammary tumor suppression." (PMID 39782693, 2025). "Inhibiting PKA activity using H‐89 and PKI peptide reversed the IL‐24‐induced apoptotic effects on a panel of breast cancer cells." (PMID 40338095, 2025). "Interleukin-24 (IL-24), an anticancer cytokine, was highly upregulated in macrophages infiltrating calcipotriol-treated mammary tumors." (PMID 39782693, 2025). "The IL-24/IL-20R axis is required for the antitumor effect of calcipotriol treatment in mammary tumors." (PMID 39782693, 2025). "We have recently shown that IL-24 induces apoptosis by activating the protein kinase A (PKA) pathway in human breast cancer cell lines." (PMID 40072085, 2025). "Collectively, these results demonstrate that CD4+ T cells and TSLP signaling are required for calcipotriol-induced antitumor response against late-stage breast cancer, which is accompanied by a significant accumulation of IL-24+ cells within the TME." (PMID 39782693, 2025). "Altogether, we identified a mechanism mediating Th2 cell immunity against established breast cancer growth, at least partly through TAMs that express IL-24, which leads to tumor suppression." (PMID 39782693, 2025). "Our findings reveal that TSLP-stimulated CD4+ Th2 cells suppress mammary tumor growth by promoting IL-24+ TAM development and IL-24–mediated tumor cell apoptosis." (PMID 39782693, 2025). "We previously demonstrated that IL-24 leads to apoptosis in cancer cells through protein kinase A (PKA) activation in human breast cancer cells." (PMID 40072085, 2025). "Collectively, our findings reveal that Th2 cell–macrophage crosstalk leads to IL-24–mediated tumor cell death, highlighting a promising therapeutic strategy to tackle breast cancer." (PMID 39782693, 2025).